KRTAP5-1 (keratin associated protein 5-1)
Description:
In the hair cortex, hair keratin intermediate filaments are embedded in an interfilamentous matrix, consisting of hair keratin-associated protein (KRTAP), which are essential for the formation of a rigid and resistant hair shaft through their extensive disulfide bond cross-linking with abundant cysteine residues of hair keratins. The matrix proteins include the high-sulfur and high-glycine-tyrosine keratins.
Synonyms: KRN1L; KRTAP5.1
Tractability: No criterion of Open Targets' tractability assessment is met for any kind of drug.
Gene: Protein-coding gene on chromosome 11 (1,584,342 to 1,585,283, reverse strand). Ensembl gene ENSG00000205869.
Pathways (Reactome):
Developmental Biology: Keratinization
Gene Ontology:
Molecular function: protein binding
Cellular component: cytosol
Genetic constraint (gnomAD): Loss-of-function variants: 3 observed, 2.73 expected, observed/expected ratio (o/e) 1.1, 90% interval 0.46 to 1.88. That is too few expected variants to judge how well the gene tolerates losing a copy. Missense variants: 298 observed, 328.06 expected, observed/expected ratio (o/e) 0.91, 90% interval 0.82 to 1. Synonymous variants: 104 observed, 123.34 expected, observed/expected ratio (o/e) 0.84, 90% interval 0.72 to 0.99.
Diseases named in the same sentence as KRTAP5-1 in open-access papers:
KRTAP5-1 is named in the same sentence as 2 diseases in open-access papers, as found by Europe PMC text mining. Sharing a sentence is not in itself a finding about the gene and the disease. The quoted sentences say what the papers report.
prostate carcinoma (1 paper, 2025). A carcinoma that arises from epithelial cells of the prostate gland. "We identified a novel gene risk panel comprising six genes (SSTR1, CA14, HJURP, KRTAP5-1, VGF, and COMP) for prostate cancer risk classification." (PMID 40592939, 2025).
tumor (2 papers, 2023 to 2025). "Further analysis revealed that the risk genes IQGAP3, KRTAP5-1, and KIF4A affected the expression of genes in relation to ICIs in tumor tissues, which may affect the treatment response to ICIs." (PMID 37370891, 2023). "Moreover, mRNA expressions of CA14, RPE65, IGSF1, SLC18 A2 and CPNE6 were significantly lower in PCa samples compared to benign samples, while HJURP, COMP, KRTAP5-1, VGF, SSTR1, LINC01612, NAALADL2-AS2, AMH and ARHGDIG were elevated in tumor samples (p < 0.05)." (PMID 40592939, 2025).